EHMT2 (euchromatic histone lysine methyltransferase 2)
Description:
Histone methyltransferase that specifically mono- and dimethylates 'Lys-9' of histone H3 (H3K9me1 and H3K9me2, respectively) in euchromatin. H3K9me represents a specific tag for epigenetic transcriptional repression by recruiting HP1 proteins to methylated histones. Also mediates monomethylation of 'Lys-56' of histone H3 (H3K56me1) in G1 phase, leading to promote interaction between histone H3 and PCNA and regulating DNA replication. Also weakly methylates 'Lys-27' of histone H3 (H3K27me). Also required for DNA methylation, the histone methyltransferase activity is not required for DNA methylation, suggesting that these 2 activities function independently. Probably targeted to histone H3 by different DNA-binding proteins like E2F6, MGA, MAX and/or DP1. Also able to mono- and dimethylate histone H1-4 at 'Lys-26' (H1.4K26me1 and H1.4K26me2, respectively). Also methylates CDYL, WIZ, ACIN1, DNMT1, HDAC1, ERCC6, KLF12 and itself.
Synonyms: BAT8; C6orf30; G9A; KMT1C; NG36; Em:AF134726.3; NG36/G9a; GAT8
Tractability: Small molecule: a structure with a bound ligand is known; a high-quality ligand is known; it has a high-quality binding pocket; it belongs to a druggable protein family. PROTAC: UniProt records ubiquitination sites on it; ubiquitination databases record sites on it; its protein half-life has been measured; a small molecule that binds it is known.
Target class: Writer; Protein methyltransferase; Epigenetic regulator
Chemical probes: A-366 (high quality), BIX-01294, BRD4770, CM-272, PD134175, PD134176, PD134177, PD134178, PD134179, PD134180, PD134181, PD134182, PD134183, PD134184, PD134185, PD134186, PD134187, PD134188, UNC 0646, UNC0638 (high quality), and 1 more
Safety:
Unwanted effects reported when the protein is acted on. In parentheses: how it was acted on, where the effect was seen, and who reports it.
agranulocytosis (source: ClinPGx)
Gene: Protein-coding gene on chromosome 6 (31,879,758 to 31,897,723, reverse strand). Ensembl gene ENSG00000204371.
Subcellular location: Nucleus; Chromosome
Subcellular location (Human Protein Atlas): Nuclear speckles; Nucleoplasm
Pathways (Reactome):
Gene expression (Transcription): ERCC6 (CSB) and EHMT2 (G9a) positively regulate rRNA expression; RNA Polymerase I Transcription Initiation; Regulation of endogenous retroelements by the Human Silencing Hub (HUSH) complex; Transcriptional Regulation by E2F6; Transcriptional Regulation by VENTX
Cellular responses to stimuli: Senescence-Associated Secretory Phenotype (SASP)
Chromatin organization: PKMTs methylate histone lysines
Gene Ontology:
Molecular function: C2H2 zinc finger domain binding; H1-4K26 methyltransferase activity; histone H3K56 methyltransferase activity; histone H3K9 monomethyltransferase activity; promoter-specific chromatin binding; protein binding; protein-lysine N-methyltransferase activity; transcription corepressor binding; histone H3K27 methyltransferase activity; histone H3K9 methyltransferase activity; histone H3 methyltransferase activity; histone methyltransferase activity; RNA polymerase II transcription regulatory region sequence-specific DNA binding; zinc ion binding
Biological process: cellular response to starvation; chromosome condensation; negative regulation of transcription by RNA polymerase II; peptidyl-lysine dimethylation; regulation of DNA replication; DNA methylation-dependent constitutive heterochromatin formation; epigenetic regulation of gene expression
Cellular component: chromatin; chromosome; nuclear speck; nucleoplasm; nucleus
Genetic constraint (gnomAD): Loss-of-function variants: 53 observed, 135.4 expected, observed/expected ratio (o/e) 0.39, 90% interval 0.31 to 0.49. The upper end of that interval is the gene's LOEUF score, 0.49, which puts it in group 2 of 6, group 1 being the genes least tolerant of losing a copy. Missense variants: 1,049 observed, 1,549.9 expected, observed/expected ratio (o/e) 0.68, 90% interval 0.64 to 0.71. Synonymous variants: 544 observed, 616.16 expected, observed/expected ratio (o/e) 0.88, 90% interval 0.82 to 0.95.
Homologues: Orthologues: chimpanzee EHMT2 (99% identical), macaque EHMT2 (98% identical), rabbit EHMT2 (96% identical), rat Ehmt2 (95% identical), mouse Ehmt2 (94% identical), guinea pig EHMT2 (94% identical), pig EHMT2 (94% identical), dog EHMT2 (94% identical), tropical clawed frog ehmt2 (62% identical), zebrafish ehmt2 (51% identical), Drosophila melanogaster G9a (29% identical), Caenorhabditis elegans met-1 (12% identical), and 11 more. Paralogues in human: EHMT1 (48% identical), KMT2A (16% identical), KMT2C (15% identical), SETDB1 (15% identical), KMT2B (15% identical), KMT2D (15% identical), NSD1 (13% identical), ASH1L (13% identical), NSD2 (12% identical), NSD3 (12% identical), SUV39H1 (12% identical), SETD1B (11% identical), and 7 more.
Diseases named in the same sentence as EHMT2 in open-access papers:
EHMT2 is named in the same sentence as 218 diseases in open-access papers, as found by Europe PMC text mining. Sharing a sentence is not in itself a finding about the gene and the disease. The quoted sentences say what the papers report.
breast cancer (97 papers, 2008 to 2026). A primary or metastatic malignant neoplasm involving the breast. "We here observed that high expression of EHMT2 was associated with the suppression of Beclin-1 in three independent and publicly available breast cancer datasets—TCGA, UNC, and NKI." (PMID 27174920, 2016). "However, when the mutational status was investigated in breast cancer patients using publicly available databases (through cBioportal), no significant frequency of gene alterations was identified for both EHMT2 and CDH10." (PMID 32292512, 2020). "We therefore investigated whether loss of CDH10 was common in breast cancer and other tumor types and whether this was associated with an increased EHMT2 expression." (PMID 32292512, 2020). "EHMT2 inhibition in cancer cells enhanced NK cell-mediated elimination of diverse cancers, including uveal melanoma, breast cancer, and pancreatic cancer." (PMID 41366520, 2026). "Here, we show that EHMT2 inhibition in uveal melanoma, breast cancer and pancreatic cancer cells promoted their NK cell-mediated tumor suppression." (PMID 41366520, 2026). "Emerging targets like H3K79me1/2/3 (DOT1L inhibitors) and H3K9me2 (G9a/EHMT2 inhibitors) are showing potential in preclinical studies of breast cancer." (PMID 39859484, 2025). "The anti-cancer effect of EHMT2 inhibition has been studied in several cancer cell lines in primary cells of breast cancer, neuroblastoma, colon, and bladder cancer, suggesting possible therapeutic options for cancer treatment." (PMID 32028644, 2020). "Treatment of breast cancer cells with BIX removed EHMT2 from the promoter of Beclin-1, leading to the reduction of H3K9me2 and resulting in an open chromatin status." (PMID 27174920, 2016). "Herein, we characterize the epigenetic regulation of Beclin-1 by EHMT2 and nuclear factor-kappa B (NF-κB) and suggest that it exhibits a relationship with tumorigenesis and patient prognosis in breast cancer." (PMID 27174920, 2016). "In conclusion, the epigenetic downregulation of a tumor suppressor gene, Beclin-1, by EHMT2, occurs in breast cancer cell lines." (PMID 27174920, 2016). "Our findings thus provide preliminary evidence for the role of EHMT2 in the progression of breast cancer via the suppression of Beclin-1." (PMID 27174920, 2016). "To this end, we have examined the effect of dual EZH2 and EHMT2 gene knockdown or enzyme inhibition in breast cancer cells." (PMID 26300989, 2015). "Additionally, it downregulates β1- and β3-integrin expression, impairing breast cancer cell migration, and decreases histone methyltransferase G9A (EHMT2) expression in alveolar rhabdomyosarcoma cells, underscoring its broad therapeutic potential." (PMID 40374533, 2025). "In addition, we show that CDH10 expression is prognostic in breast cancer and that it is inversely correlated to EHMT2 (G9a) transcript levels in many tumor-types, including breast cancer." (PMID 32292512, 2020). "Our finding that EHMT2 is overexpressed in breast cancer cells suggests that the development of a novel EHMT2 inhibitor may provide a mechanism for activating an autophagy initiating gene, Beclin-1, in cancer cells." (PMID 27174920, 2016). "Therefore, we assessed the relationship between the expression of EHMT2 and Beclin-1 and the survival rate of breast cancer patients from two large datasets, the Netherlands Cancer Institute (NKI) and University of North Carolina (UNC) cohorts." (PMID 27174920, 2016). "Furthermore, EHMT2 showed a reciprocal expression pattern with Beclin-1 in The Cancer Genome Atlas (TCGA) of breast cancer patients." (PMID 27174920, 2016). "Additionally, other studies have identified the role of EHMT2 in promoting breast cancer." (PMID 41366520, 2026). "Moreover, levels of EHMT2 and Beclin-1 expression may represent useful prognostic markers for patients with breast cancer." (PMID 27174920, 2016). "The ability of EHMT2 and CDH10 mRNA to stratify breast cancer patients was analysed in the KM Plotter database." (PMID 32292512, 2020).
breast cancer (continued). "The breast cancer samples were then further stratified into the different molecular subtypes and the expression ratios of tumor to normal tissue for CDH10 and EHMT2 were compared as previously." (PMID 32292512, 2020). "Publicly available databases were examined to evaluate the importance of G9a (EHMT2) and CDH10 expression in breast cancer." (PMID 32292512, 2020). "In clinical breast cancer cohorts, EHMT2 (Euchromatic histone-lysine N-methyltransferase 2), a histone methyltransferase, was overexpressed, and EHMT2 knockdown upregulates the expression of HSP60, thus inducing cell apoptosis." (PMID 31557887, 2019). "In this present study, we showed that the expression of ATGs was elevated after the inhibition of EHMT2 by BIX in PCR array analysis, and established that the epigenetic transcriptional activation of Beclin-1 occurred in breast cancer cells." (PMID 27174920, 2016). "Our findings indicated that high EHMT2 and low Beclin-1 expression correlated with reduced overall and recurrence-free survival in patients with breast carcinoma in the UNC and NKI breast cancer datasets." (PMID 27174920, 2016). "Agilent microarrays were used to perform gene expression profiling in MDA-MB-231 breast cancer cells after 24 h of treatment with the hit compound HKMTI-1-005, the EZH2 inhibitor GSK343 and EHMT2 inhibitor UNC0638." (PMID 26300989, 2015). "EHMT2 transcript levels were found not to be a good marker for relapse-free survival in breast cancer patients." (PMID 32292512, 2020). "EHMT2 or G9a is a histone methyl transferase that primarily catalyzes mono- and dimethylation of histone H3K9 to afford H3K9me1/me2, being overexpressed in several cancers, including head and neck squamous carcinoma, breast cancer, and aggressive ovarian and bladder cancers." (PMID 35890123, 2022). "Through the use of a breast cancer (MDA-MB-231) cell assay based on the re-expression of epigenetically silenced genes, we report the identification of hit compounds that phenocopy the effects of dual EZH2/EHMT2 pharmacological inhibition and dual SiRNA gene knockdown." (PMID 26300989, 2015).
lung carcinoma (60 papers, 2008 to 2025). "It nevertheless remains clear that cholesterol biosynthesis, EHMT2 transcriptional control, and autophagy are linked in ways that relate to proliferative activity and cell viability, likely essential to lung cancer-related tumorigenesis." (PMID 32028644, 2020). "Similarly, EHMT2/G9a is overexpressed in aggressive lung cancer cells and is linked to unfavorable prognosis." (PMID 38525426, 2024). "Overexpression of EHMT2 may be associated with a poor prognosis in patients with various types of malignant cancers including lung cancer, ovarian cancer, esophageal squamous cell carcinoma, and so on 14-16." (PMID 33442400, 2021). "Paradoxically, EHMT2 inhibition by BIX01294 induces cell death in lung cancer cells via promoting cholesterol biosynthesis, and 25HC reduces BIX01294-induced cell death." (PMID 39349433, 2024). "Overexpression of EHMT2 has been observed in various cancers including esophageal squamous cell carcinoma, aggressive lung cancer, multiple myeloma, brain cancer, ovarian carcinoma, etc.." (PMID 34344448, 2021). "In lung cancer, overexpressed EHMT2 was reported to contribute to rapid proliferation and invasion, suggesting that it can be a potential therapeutic target." (PMID 32028644, 2020). "Next, we investigated the effects of EHMT2 in lung cancer cell lines H1299 and A549 to understand the role of EHMT2 in cancer cell proliferation." (PMID 32028644, 2020). "Increased EHMT2 protein expression has been reported in lung cancer tissues, including adenocarcinomas and squamous cell carcinomas, when compared to normal control tissues." (PMID 33050946, 2020). "Overexpression of EHMT2 has been reported in various cancers including ovarian cancer and lung cancer." (PMID 32028644, 2020). "EHMT2 is overexpressed and amplified in various cancers including leukaemia, prostate carcinoma, and lung cancer, with gene knockdown of EHMT2 inhibiting cancer cell growth in these tumour types." (PMID 26300989, 2015). "In addition, in breast, bladder, and lung cancer, EHMT2 knockdown was involved in cell apoptosis and cell migration/invasion." (PMID 34972816, 2022). "The discovery that EHMT2 functions to directly regulate Wnt signaling deepens our mechanistic understanding of EHMT2 activity and presents potential opportunities for targeting in both lung cancer, as well as other AT2-mediated lung pathologies." (PMID 35983994, 2022). "Previously, alteration of EHMT2 expression has been frequently observed in various human cancer types such as ovarian cancer, melanoma, esophageal squamous cell carcinoma, aggressive lung cancer, brain cancer." (PMID 34344448, 2021). "Furthermore, they showed that EHMT2 promoted the invasion and metastatic potential of lung cancer cells through H3K9 di-methylation (H3K9me2) and silencing of the promoter of EPCAM, a cell adhesion molecule." (PMID 33050946, 2020). "Based on our findings, EHMT2 seems to directly regulate transcriptional expression of SREBF2, a master regulator for cholesterol biosynthesis, in effect lowering cholesterol in lung cancer." (PMID 32028644, 2020). "The inhibitors discussed in relation to resensitising lung cancer cells target either EZH2 (GSK126, GSK343, DZNep, GSK343, EPZ011989), G9a/EHMT2 (UNC0642, UNC0638), DOT1L (SGC0946), SMYD3 (EPZ031686) or SMYD2 (BAY-598), some of which were also discussed in this review." (PMID 39703687, 2024). "Metformin suppressed the protein and mRNA expressions of euchromatic histone lysine methyltransferase 1, 2 (EHMT1, EHMT2), enhancer of zeste 1, 2 polycomb repressive complex 2 subunit (EZH1, EZH2), lysine methyltransferase 2A, 2B (MLL1, MLL2), and WD repeat domain 82 (WDR82) in lung cancer cells." (PMID 33578894, 2021).
gastric cancer (28 papers, 2017 to 2025). A primary or metastatic malignant neoplasm involving the stomach. "For instance, Olaparib-resistant ovarian adenocarcinoma cells and 5-FU resistant gastric cancer tissue both showed an increase in EHMT2 protein expression." (PMID 38827317, 2024). "More specifically, a study of 107 gastric cancer tissues with their normal counterparts found that EHMT2 is significantly overexpressed in gastric cancer tissues and correlates with advanced clinical stage and lymph node metastasis." (PMID 33050946, 2020). "Clinicopathologic associations of EHMT2, a transcriptional repressor that methylates H3K9 and H3K27, have been reported in NSCLC, gastric cancer, hepatocellular carcinoma (HCC), ovarian cancer, and SCCHN." (PMID 33050946, 2020). "While further investigation into the role of EHMT2 in gastric cancer is warranted, these findings highlight important prognostic associations." (PMID 33050946, 2020). "Overexpression of EHMT2 is also encountered in gastric cancer and has been shown to correlate with aggressive pathologic features." (PMID 33050946, 2020). "Stable over-expression of miR-584-3p resulted in increased binding of AGO2 and epigenetic markers EZH2, EHMT2, H3K27me3 and H3K9me2, and decreased binding of YY1 to MMP-14 promoter in gastric cancer cells, which was attenuated by knockdown of AGO2." (PMID 28827574, 2017). "The histone methyltransferase (EHMT2) G9a is an NR4A1-regulated gene in RMS and the observation that kaempferol decreased expression of G9a in gastric cancer cells suggested that kaempferol may be an NR4A1 ligand acting as an antagonist." (PMID 34906197, 2021). "In addition, the induction of cytoplasmic RUNX3 retention under hypoxic culture condition in gastric cancer cells occurs via the upregulation of histone deacetylase (HDAC) and histone methyltransferase (HMT), euchromatic histone-lysine N-methyltransferase 2 (EHMT2/G9a)." (PMID 38683453, 2024).
hepatocellular carcinoma (26 papers, 2014 to 2023). A malignant tumor that arises from hepatocytes. "In this study, we aimed to investigate the roles of EHMT2 in the pathogenesis of hepatocellular carcinomas and identify the underlying mechanisms." (PMID 34344448, 2021). "The results of our previous study also revealed that TRERNA1 promotes hepatocellular carcinoma (HCC) metastasis via recruitment of the EHMT2/SNAI1 complex to suppress CDH1." (PMID 35031597, 2022). "Similarly, a prior study revealed that lncRNA TRERNA1 was able to recruit EHMT2 onto the CDH1 promoter region to promote hepatocellular carcinoma development." (PMID 35419917, 2022). "Our particular interest is the PKMT G9a (also known as KMT1C, EHMT2), which is a histone 3 lysine 9 (H3K9) specific methyltransferase that is overexpressed in many cancers including leukemia, hepatocellular carcinoma and pulmonary carcinoma." (PMID 28968981, 2017).